HIF1A (hypoxia inducible factor 1 subunit alpha)
Diseases named in the same sentence as HIF1A in open-access papers (continued):
Sharing a sentence is not in itself a finding about the gene and the disease.
tumor (continued). "The results of this study were supported by another study where HIF-1α expression showed a significant correlation with TAM infiltration in tumor biopsies from 236 GC patients." (PMID 35681691, 2022). "Upon HIF1α knockdown, the number of tumor cells crossing the membrane was significantly decreased, and this inhibition partially retrieved after ZEB1 overexpression." (PMID 35589690, 2022). "In parallel, human NK cells, isolated and sequenced from non-small cell lung cancer patients, had higher HIF1a expression and lower IFNγ expression when NK cells were isolated from within the tumor compared to the peritumor region." (PMID 35414042, 2022). "For example, HIF-1a is upregulated in HNSCC cells and positively associated with tumor aggressiveness, enhanced tumor angiogenesis and poor prognosis." (PMID 35945448, 2022). "Due to the connection between hypoxia and cancer, it has also been demonstrated that HSF1 and HIF1A are closely related to tumor formation." (PMID 36347941, 2022). "HIF1α plays crucial roles in the regulation of energy metabolism, angiogenesis and other processes in the tumor microenvironment, enabling cancer cells to undergo EMT under metabolic stress and gaining greater proliferation and metastasis capacities." (PMID 35589690, 2022). "In cancer cells, an increase in ROS stabilizes hypoxia-inducible factor-1α (HIF1α), which enhances glucose catabolism and allows for tumor progression." (PMID 36555756, 2022). "Oxygen shortage not only activates hypoxia signaling pathways such as HIF1α, more profoundly, up to 50% of hypermethylation events in solid tumors are also due to hypoxia, and these events confer a selective advantage for tumor growth." (PMID 34976191, 2022). "It is known that the regulation of HIF-1α is disturbed as a response to the cellular hypoxia status and/or as a subsequent reflection of genetic alterations that occur in tumor pathophysiology, including tumor invasion, angiogenesis, and cell survival." (PMID 35399691, 2022). "Taken together, it is highly likely that a combination of HIF-1α inhibitors with immune checkpoint inhibitors would significantly improve anti-tumor immunity." (PMID 35805044, 2022). "The aim of this study was to define the essential mRNAs and miRNAs regulated by HIF1A and dissect their functions, interactions, and tumor-infiltrating immune cells in HCC." (PMID 35774500, 2022). "It is noteworthy that tumor-associated macrophages (TAM) are important components of hypoxic TME, and TAM enhances its inhibitory effect on T cells by expressing HIF-1α." (PMID 36263421, 2022). "Studies have shown that the expression of hypoxia induce factor 1α (HIF1α) is up-regulated in a variety of tumor tissues, which is related to multiple metabolic reprogramming of tumor cells." (PMID 35912204, 2022). "In this review, we discussed the radiation-induced stimulation of anti-tumor immunity and the radiation-induced suppression of anti-tumor immunity mediated mainly by HIF-1α." (PMID 35805044, 2022). "In this way, hypoxia helps the cells of the primary tumor to escape the hypoxic region and migrate to a distal site to form a secondary tumor by regulating HIF-1α." (PMID 36014432, 2022). "Digoxin, which can inhibit HIF-1α and block tumor growth, has shown therapeutic potential in a clinical trial (NCT01763931) for breast cancer treatment." (PMID 35805056, 2022). "We also found a positive relationship between SOCS5 and HIF-1α, the core molecule of the hypoxic tumor microenvironment, at the RNA and protein levels via the cBioPortal website and the Human Protein Atlas website." (PMID 36319626, 2022). "Together, a regulatory circuit consisting of the STIM1-mediated SOCE mechanism and phosphorylated p300-stablized HIF-1α can promote tumour proliferation under hypoxic conditions." (PMID 35269437, 2022).
tumor (continued). "Here we report that targeting of HIF-1α suppressed PD-L1 expression on tumor cells and tumor-infiltrating myeloid cells, but unexpectedly induced PD-L1 in normal tissues by an IFN-γ–dependent mechanism." (PMID 35239514, 2022). "The NK cells in the irradiated tumor microenvironment are exhausted, wherein the immunosuppressive signals are highly activated by HIF-1α." (PMID 35805044, 2022). "In conclusion, swimming significantly attenuates the growth of CT-26 cell-derived tumors in vivo, reduces tumor angiogenesis, and downregulates the expression of HIF-1α, VEGFA, and its receptor VEGFR2." (PMID 35291563, 2022). "The average D, D*, f, perfusion (f × D*) and R2* values were calculated for the ROIs in the tumor and normal brain regions with different HIF-1α levels and used in further analysis." (PMID 35785202, 2022). "It had been reported that CAFs were involved in the regulation of tumor HIF1α signaling pathway to promote tumor progression." (PMID 35589690, 2022). "Previous studies have also indicated that HIF-1α extremely promoted tumor growth and played a key role in the development of multiple tumors." (PMID 36091021, 2022). "Single-cell and bulk RNA-seq analysis shows that HIF1A-inhibited tumor cells can increase glycogen synthesis and lead to an inflammatory response that contributes to tumor formation in pancreatic tumors." (PMID 35281061, 2022). "Inhibitors of HIF-1α can suppress the proliferation, growth, metastasis and invasion of tumor cells." (PMID 35311089, 2022). "HIF-1α plays crucial roles in hypoxia-induced malignant transformation of many tumor cells, including the EMT phenotype and the formation of VM." (PMID 35309179, 2022). "Firstly, GBM tumor cell-induced IL-1β drives the HIF-1α-IL-1β autocrine loop to maintain a persistently elevated IL-1β level that activates RelB/p50 complexes, thus attracting or polarizing GAMs." (PMID 35572545, 2022). "After establishing the tumor-bearing mouse model, Par was administered by gavage to measure the tissue levels of P50 and HIF-1α, followed by plotting of tumor growth curves." (PMID 36260873, 2022). "The combined inhibition of PI3K/Akt/mTOR and the Shh dual pathways and knockout or inhibition of HIF-1α can help reduce the migration ability of tumor cells and prolong the postoperative survival of patients." (PMID 35935338, 2022). "Carbonic anhydrases, controlled by oxygen levels via the HIF1α, are overexpressed in several solid tumors, with a fundamental role in tumor pH homeostasis and very low, or negligible expression, in normal tissues." (PMID 36672576, 2022). "In the current study, the increase of HIF-1α after exposure to RT in GB patients is explained that GB is a malignant tumor that is highly aggressive and hypoxic." (PMID 36121548, 2022). "The increased expression of Pvt1 which is induced by HIF-1α under hypoxia causes the down-regulated expression of Arg-1 and ROS in PMN-MDSCs, and assists T cells to suppress tumor growth in tumor-bearing mice." (PMID 36569895, 2022). "Transcription factor networks identified in our data support a role for these transcriptions factors, as well as HIF1α, in the spleen-to-tumor transition." (PMID 36480485, 2022). "SABR also induces vascular damage and obstructs blood flow, thereby increasing tumor hypoxia and upregulation of hypoxia-inducible factors HIF-1α and HIF-2α, master transcription factors for the cellular response to hypoxia." (PMID 35805044, 2022). "The expression levels of N-cadherin, Vimentin, Snail, MMP9 and HIF-1α were significantly decreased in the xenograft tumor tissues from mouse model injected with M2 cells treated with OL, when compared with those of the control group." (PMID 36050634, 2022). "Experimental results from murine xenograft tumor model support the crucial role of HIF-1α in cancer metastasis." (PMID 36344992, 2022). "A possible theory is the presence of a feedback mechanism between markers/genes within the tumor and HIF-1α." (PMID 35207237, 2022).
tumor (continued). "In their functional studies, HIf1a knock down reduced vasculogenic mimicry, tumor cell migration, invasion and would closure in a scratch assay." (PMID 36203599, 2022). "Animal models confirm that incomplete ablation promotes angiogenesis through the HIF-1α/VEGF signal pathway leading to tumor invasion and metastasis." (PMID 36081558, 2022). "The protein levels of hypoxia inducible factor 1α (HIF-1α) in primary tumors and circulating tumor cells of CRC patients were detected by immunohistochemistry and immunofluorescence." (PMID 34998404, 2022). "KDM4C was shown to promote tumor angiogenesis by transcriptionally activating the HIF1α/VEGFA signaling pathway." (PMID 35633893, 2022). "In human pancreatic cancer cell lines, in vitro, low ascorbic acid concentrations (25 μM) reduced HIF1α expression and suppressed tumor growth under hypoxic conditions." (PMID 36203466, 2022). "Decreasing NRF2 in a hypoxic tumor reduces hypoxia-mediated deleterious metabolic activity of HIF1α." (PMID 36213236, 2022). "Tumour sites located at the base of the mouth appear to have stronger HIF-1α expression than tumours of the tongue." (PMID 36077667, 2022). "Consistent with this, the tumor tissues from mice injected with Bif showed clear localization of the (Cy3-labeled) bacteria in the hypoxic zone (Alexa Fluor 488-labeled HIF-1α) of the tumors." (PMID 35366890, 2022). "Fortunately, emerging agents targeting HIF-2α are promising anti-tumor therapeutics, providing alternative candidates for hypoxia-targeted drugs when all HIFs beyond HIF-1α are taken into consideration." (PMID 35798726, 2022). "It has been established that the transcription factor HIF-1α promotes aerobic glycolysis and regulates tumour invasion and metabolism." (PMID 36591282, 2022). "Therefore, succinate accumulation through inhibition of prolyl hydroxylase causes HIF1α stabilization and its translocation to the nucleus, which might enhance angiogenesis, resistance against apoptosis, and the activation of genes involved in tumor invasion." (PMID 35089096, 2022). "Next, we used shRNA to compare the effects of Hif1a- or Pdl1-targeted knockdown in E0771 cells on the tumor growth kinetics in immunocompetent or immunodeficient recipients." (PMID 35239514, 2022). "Our observations on the correlation between HIF-1α and PD-L1 resonate with experimental observations in tumor-bearing mice reporting that PD-L1 upregulation in hypoxia depended on HIF-1α activity." (PMID 36354714, 2022). "The hypoxia-inducing factor HIF1α has been depicted in a series of prior works to have a core role in tumor recurrence and metastasis." (PMID 36473847, 2022). "The removed tumor tissues were subjected to Western blot, and it was confirmed that the protein expression of HIF-1α and its downstream glycolytic genes GLUT1, HK2 and PDK1 in the HNK treatment group was significantly lower than that in the control group." (PMID 35350760, 2022). "In conclusion, we demonstrated that in LUAD cells, highly expressed mPRα enhances the activation of cAMP/JAK/STAT3 signaling and increases HIF1α-induced VEGF secretion into the tumor microenvironment, promoting HUVEC migration and tube formation under hypoxia." (PMID 35123491, 2022). "Impact of acute hypoxia-induced mitochondrial ROS activates STIM1 puncta formation and SOCE activation through HIF1α and subsequent Ca2+ signal benefits tumor cell proliferation." (PMID 36154922, 2022). "Experimental evidence implicates reactive oxygen species (ROS) generation in the hypoxic stabilization of hypoxia-inducible factor (HIF)-1α and in the subsequent expression of promoters of tumor invasiveness and metastatic spread." (PMID 36354671, 2022). "And tumor angiogenesis perfusion is reduced, which in turn exacerbates the hypoxic environment and maintains HIF-1α stability." (PMID 36532768, 2022). "In patients with cSCC, HIF-1α was expressed in 100% of the tumor areas, while only 90% of their healthy skin biopsies were positive." (PMID 35956111, 2022).
tumor (continued). "The synergic effect of gemcitabine and HIF1α-siRNA loaded in GE-11-modified liposomes reduced the tumor fourfold more than in the control group." (PMID 35456655, 2022). "After oxygen treatment, there was not only a reduction in tumor growth in the mouse model, but also a decrease in HIF-1α levels, along with the number of exosomes secreted by these granulocytic cells." (PMID 35681719, 2022). "During hypoxia, tumor cells express hypoxia inducible factor-1 alpha (HIF-1α) to excessively activate vascular endothelial growth factor (VEGF) for promoting angiogenesis." (PMID 35631488, 2022). "Moreover, HIF-1α/STAT5B signaling could also be directly linked to tumor epileptogenicity." (PMID 36295510, 2022). "SIRT1 inhibits HIF-1α activity by blocking p300 recruitment, leading to downregulated glycolysis and retarded tumor growth." (PMID 34050894, 2022). "It has been reported by many studies that hypoxia-inducible factor-1α (HIF-1α) induces hypoxia and regulates tumor cell adaptation to hypoxia in response to changes in oxygen." (PMID 35280516, 2022). "Hypoxia activates related pathways by inducing HIF-1α protein expression and nuclear metastasis, promoting tumor invasion and metastasis, consistent with our data." (PMID 36319626, 2022). "This suggests positive feedback, whereby tumor cells produce lactic acid (via enhanced glycolysis), which stabilizes HIF-1α, in turn increasing tumor B cell EVs, which results in immunosuppression." (PMID 35563739, 2022). "Our results indicate that lactate promotes sEV release from tumor cells in a HIF-1α-dependent manner." (PMID 36531060, 2022). "As a result, HIF-α activation in response to tumor hypoxia can drive tumor progression, making HIF-1α and HIF-2α the primary targets for therapeutic intervention." (PMID 35267567, 2022). "Critically, the presence of hypoxia reprograms tumor cells through multiple proteins, such as hypoxia-inducible factor (HIF)-1α." (PMID 35267480, 2022). "In that study, XBP1s was shown to contribute to tumor progression by activating HIF-1α, a target we also found to be upregulated by FOXK2, downstream of IRE1α." (PMID 35349489, 2022). "Based on the findings of HIF1α expression level and tumor pathological stage, we further evaluated the relationship between HIF1α expression level and survival prognosis of pan-cancer patients by the Cox regression analysis." (PMID 35860430, 2022). "Stabilized HIF1α integrates to hypoxia response elements (HREs) and then triggers the transcription of downstream target genes that are involved in tumor angiogenesis, metastasis, and glucose metabolism." (PMID 35589690, 2022). "The tumoural microenvironment presents fluctuations in oxygen levels within the tumour; hence, HIF-1α has a vital role as an oxygen sensor in cancer cells." (PMID 34557995, 2022). "Our data suggest that targeting HIF-1α fortifies the immune tolerance function of the PD-1/PD-L1 checkpoint in normal tissues but abrogates its immune evasion function in the tumor microenvironment to achieve safer and more effective immunotherapy." (PMID 35239514, 2022). "Overall, we indicated the presence of a HIF1A-RRAGB-mTORC1 positive feedback loop in CRC that boosted tumor progression." (PMID 35739524, 2022). "Altogether, these findings indicate that the tumour microenvironment‐induced stabilization of HIF‐1α is involved in the regulation of FOXM1 expression status." (PMID 35656815, 2022). "RNA levels of HIF1A were significantly higher in all tumor types compared with normal pituitary tissue, with an overall elevation of 2.4-fold (p=0.0004)." (PMID 35600354, 2022). "Transient glycolytic activation of peritumoral monocytes induced sustained expression of CA12 on tumor-infiltrating macrophages via autocrine cytokines and HIF1α pathways." (PMID 35362480, 2022).
tumor (continued). "HIF-1α is overexpressed in tumor cells, enabling several adaptations like the upregulation of angiogenic factors and glycolytic enzymes to maintain ATP production in the absence of more complex pathways like fatty acid oxidation." (PMID 35163264, 2022). "Our results showed higher HIF-1α expression in the central tumor area than in peripheral tumor parts and normal tissue, and the perfusion, f, and D* values in the central tumor parts were lower than those in the peripheral parts." (PMID 35785202, 2022). "As illustrated by IHC, tumor tissues displayed an increase expression of HIF1α and VEGF compared to the adjacent normal tissues." (PMID 35355718, 2022). "We injected 5-FU, the HIF-1α inhibitor IDF-11774 or saline in subcutaneous tumor models in nude mice starting one week after implantation." (PMID 34998404, 2022). "HIF-1α transcriptionally regulates a battery of genes that are pivotal for tumor angiogenesis and metastasis, including the pro-angiogenic vascular endothelial growth factors (VEGFs)." (PMID 36296726, 2022). "Inhibition of angiogenesis by metformin has been linked to suppression of HIF-1α via AMPK signaling, or to inhibition of platelet-derived growth factor β (PDGF-β) that lead to normalization of tumor vasculature." (PMID 36582801, 2022). "HIF-1α, the principal regulator of hypoxia, mediates a variety of biological processes in tumor cells, including EMT." (PMID 36050634, 2022). "The authors also reported an interesting observation; although HIF-1α inhibition blocked PD-L1 expression at the tumor site, it induced PD-L1 in normal tissues." (PMID 35499071, 2022). "Since HIF-1α is also regulated by NF-κB transcription, it can be said that NF-κB-HIF-1α is the major regulatory signal of tumor glycolysis." (PMID 36260873, 2022). "Either long-term hypoxia or increased expression of the protein coiled-coil helix domain-containing protein 4(CHCHD4) by U2OS tumor cells in normoxia resulted in an accumulation of mitochondria perinuclearly, which was dependent upon HIF-1α activation." (PMID 36671435, 2022). "Taken together, the data support the conclusion that echinomycin confers immunotherapeutic effects in vivo by targeting the HIF-1α/PD-L1 axis in tumor cells." (PMID 35239514, 2022). "HIF1A knock-down slowed down tumor growth and diminished the proportion of Ki-67-positive cells in both WT and 5-FU-R groups." (PMID 34998404, 2022). "HIF1α overexpression can trigger tumor cells to secrete chemoattractants, including stromal-derived factor 1α (SDF-1α or CXCL12), CXCL5, and CCL2." (PMID 36419156, 2022). "Subcutaneous mouse models of lymphoma and lung cancer have shown that deletion of HIF1α in NK cells delayed tumor growth." (PMID 35414042, 2022). "Recently, it has been shown that both HIF-1α and extracellular adenosine can counteract tumor-reactive T-cells via A2A/A2B adenosine receptors." (PMID 35625561, 2022). "Second, tumor-derived exosomes can promote epithelial-to-mesenchymal transition (EMT) and tumor metastasis by activating the resting cancer cells to aggressively metastasize via multiple inducible signaling molecules like Notch1 and HIF1α." (PMID 35757760, 2022). "The hypoxia-inducible factor 1 alpha (HIF-1α) plays a vital role in the hypoxic response in tumor cells, partially through the upregulation of VEGF." (PMID 35743145, 2022). "Ascorbic acid concentrations in human tumor samples were negatively connected with HIF1α expression in colon cancer, with higher ascorbic acid concentrations associated with prolonged recurrence-free survival." (PMID 36203466, 2022). "Immune checkpoints are targets of immunotherapy, and researchers have found that patients with tumors co-expressing HIF-1α, a subtype of HIF, and PD-L1, an immune checkpoint, have a high risk of tumor recurrence and metastasis as well as lethality." (PMID 35924146, 2022).